SIRT7 (sirtuin 7)
Diseases named in the same sentence as SIRT7 in open-access papers (continued):
Sharing a sentence is not in itself a finding about the gene and the disease.
metastatic disease (5 papers, 2015 to 2023). "In epithelial prostate carcinomas, high SIRT7 levels are associated with aggressive cancer phenotypes, metastatic disease and poor prognosis." (PMID 31196136, 2019). "In epithelial prostate carcinomas, high SIRT7 levels are associated with aggressive cancer phenotypes, metastatic disease and poor patient prognosis." (PMID 31196136, 2019). "High SIRT7 expression is associated with aggressive cancer phenotypes, metastatic diseases and poor patient prognosis; down-regulating SIRT7 reverses the metastatic properties of epithelial and mesenchymal cancer cells." (PMID 30510540, 2018). "In epithelialprostate carcinomas, high SIRT7 levels are associated with aggressive cancerphenotypes, metastatic disease, and poor patient prognosis, and depletion of SIRT7can reprogram these cells to a less aggressive phenotype." (PMID 25923013, 2015).
non-small cell lung carcinoma (5 papers, 2019 to 2024). A group of at least three distinct histological types of lung cancer, including non-small cell squamous cell carcinoma, adenocarcinoma, and large cell carcinoma. "SIRT7-mediated autophagic response plays a protective role against cell death and the inhibition of SIRT7 has a potential to improve the efficacy of anti-metabolic therapy in non-small cell lung cancer cells." (PMID 35387119, 2022). "In human non-small cell lung cancer, depletion of SIRT7 can inhibit gemcitabine-induced autophagy and significantly sensitize cancer cells to gemcitabine therapy in vivo and in vitro." (PMID 32019578, 2020). "In human non-small cell lung cancer cells, SIRT7 depletion inhibited autophagy and promoted gemcitabine-induced cell death." (PMID 32019578, 2020). "miR-3666 targets Sirtuin 7 to inhibit the growth of non-small cell lung carcinoma cells, by promoting the apoptotic signal transduction pathway." (PMID 33149754, 2020). "The study unveils a unique mechanism by which SIRT7 promotes proliferation of non-small-cell lung cancer that may be exploited to increase cellular levels of ARF for antitumor therapies in cancers with intact ARF expression." (PMID 38870055, 2024).
Stroke (5 papers, 2014 to 2025). Sudden impairment of blood flow to a part of the brain due to occlusion or rupture of an artery to the brain. "In the future, significant proteins including UBC, CUL3, APP, NEDD8, JUP, SIRT7, etc., can be potent drug targets for first aid and emergency treatment within 24 h post-stroke." (PMID 26679092, 2015). "Furthermore, astragaloside IV not only binds to SIRT7 but also increases the expression of SIRT7, which promotes angiogenesis via the SIRT7/VEGFA signaling pathway to facilitate post-stroke brain tissue repair." (PMID 40356977, 2025).
diabetic nephropathy (4 papers, 2022 to 2024). "Notably, SIRT7 and ELK1 mutually inhibit each other at the DAPK3 promoter; thus, forced SIRT7 overexpression may kill the hyperglycemic memory of the ELK1-DAPK3 axis and alleviate diabetic nephropathy." (PMID 37676263, 2024).
head and neck squamous cell carcinoma (4 papers, 2018 to 2025). A squamous cell carcinoma that arises from any of the following anatomic sites: lip and oral cavity, nasal cavity, paranasal sinuses, pharynx, larynx, and salivary glands. "SIRT7 plays crucial regulatory roles in the development of various cancers, for example, head and neck squamous cell carcinoma." (PMID 41114868, 2025).
invasive breast carcinoma (4 papers, 2017 to 2024). A carcinoma that infiltrates the breast parenchyma. "Similarly, a pattern of decreased SIRT7 expression was observed in higher grade malignant invasive breast cancer samples." (PMID 34433808, 2021).
oral squamous cell carcinoma (4 papers, 2018 to 2024). "Later studies report that SIRT7 has similar roles in oral squamous cell carcinoma (OSCC): it is successively downregulated in OSCC and inhibits EMT in vitro and lung metastasis in vivo; miR-770 promotes OSCC metastasis by targeting SIRT7 and inhibiting the downregulation of SMAD4 signaling." (PMID 37676263, 2024).
osteoporosis (4 papers, 2018 to 2025). A condition of reduced bone mass, with decreased cortical thickness and a decrease in the number and size of the trabeculae of cancellous bone (but normal chemical composition), resulting in increased fracture incidence. "Resveratrol’s beneficial function was mediated via NF-κB signaling modulated by miR-193a/SIRT7 to alleviate osteoporosis in vivo." (PMID 41226117, 2025). "Plasma samples and bone tissues from patients with osteoporosis contain elevated miR-193a but a decreased SIRT7 level." (PMID 37676263, 2024). "miR-193a inhibits BMSC osteogenic differentiation and induces osteoporosis by targeting SIRT7 and promoting NF-κB signaling." (PMID 37676263, 2024). "They found miR-193a overexpressed and SIRT7 downregulated in osteoporosis." (PMID 41226117, 2025). "Finally, SIRT7 could be a potential target for the treatment of osteoporosis." (PMID 30026585, 2018).
sarcoma (4 papers, 2015 to 2026). A usually aggressive malignant neoplasm of the soft tissue or bone. "SIRT7 exhibited differential expression across 17 cancer types, with high expression associated with poor survival in six cancer types; however, it surprisingly correlated with better outcomes in sarcoma." (PMID 41642899, 2026). "Interestingly, SIRT7 isalso important for maintaining the invasiveness and metastatic potential ofnon-epithelial sarcoma cells." (PMID 25923013, 2015). "Importantly, however, our finding that SIRT7 affects the invasive properties ofHT1080 sarcoma cells suggests thatSIRT7 must also impinge on metastasis regulatory pathways that operate inmesenchymal cancers, independent of EMT." (PMID 25923013, 2015).
thyroid (4 papers, 2022 to 2025). "Specifically, SIRT7 promotes thyroid oncogenesis by inducing phosphorylation of Akt (also known as Protein Kinase B) and ribosomal protein S6 kinase beta‐1 (p70S6K1), whose activation has been shown to promote thyroid tumorigenesis." (PMID 39215785, 2025). "SIRT7 promotes thyroid tumorigenesis through DBC1/SIRT1 axis phosphorylation and activation of AKT and p70S6K1." (PMID 36523971, 2022). "Additionally, SIRT7 represses DBC1 transcription to promote thyroid tumorigenesis by binding to the promoter of DBC1." (PMID 35913115, 2022).
colon cancer (3 papers, 2020 to 2024).
endothelial dysfunction (3 papers, 2022 to 2024). In vascular diseases, endothelial dysfunction is a systemic pathological state of the endothelium (the inner lining of blood vessels) and can be broadly defined as an imbalance between vasodilating and vasoconstricting substances produced by (or acting on) the endothelium. "The potential miR-335-5p-based diagnostic or SIRT7-targeted therapeutic application in age-related diseases still depends on future trials with more specific design and more quantitative results, especially those focusing on the downstream mechanism of SIRT7 improving endothelial dysfunction." (PMID 34981113, 2022). "Herein, these in vitro results support the role of the miR-148a-3p/SIRT7 axis in counteracting mitochondrial damage and apoptosis during endothelial inflammation, unveiling a novel target for future strategies to prevent endothelial dysfunction." (PMID 38791128, 2024). "SIRT7 overexpression reverted endothelial dysfunction and maintained cell homeostasis by regulating proliferation, migration, and tube formation in pulmonary arterial endothelium cells and exerted a rescue effect against oxidative stress-induced HUVECs." (PMID 38791128, 2024). "Overall, these results unveil the ability of miR-148a-3p to prevent endothelial damage, indicating miR-148a-3p/SIRT7 as epigenetic regulators to consider against endothelial dysfunction induced by inflammatory stimuli." (PMID 38791128, 2024). "It found that the miR-335-5p inhibitor attenuated the down-regulation of SIRT7 expression induced by oxidative stress in HUVECs, and SIRT7 overexpression exerts a rescue effect against miR-335-5p-induced endothelial dysfunction." (PMID 34981113, 2022). "Therefore, our understanding of the precise contribution of SIRT7 to endothelial dysfunction remains limited." (PMID 38791128, 2024). "Finally, the expression of miR-148a-3p and SIRT7 protein levels on the inflammatory state induced by IL-6 was then evaluated, given their emerging role during endothelial dysfunction." (PMID 38791128, 2024). "In addition, although the ability of miRNAs to regulate SIRT7 expression has been described in different experimental models, to date, no report has explored the interaction between miR-148a-3p and SIRT7 in inflammatory-related endothelial dysfunction." (PMID 38791128, 2024). "The activity of SIRT7 in endothelial dysfunction has been related to miRNA regulation." (PMID 38791128, 2024). "Moreover, the miR-335-5p inhibitor attenuated the downregulated SIRT7 expression induced by oxidative stress, and SIRT7 overexpression rescued miR-335-5p-induced endothelial dysfunction." (PMID 36646384, 2023).
esophageal squamous cell carcinoma (3 papers, 2023 to 2025). Esophageal squamous cell carcinoma (ESCC) is a type of esophageal carcinoma (EC) that can affect any part of the esophagus, but is usually located in the upper or middle third. "Among these CRLs, esophageal squamous cell carcinomas were reported to be suppressed by lncRNA LINC00886 through the SIRT7/ELF3/miR-144 pathway." (PMID 36674979, 2023). "SIRT7 was also found to be downregulated in esophageal squamous cell carcinoma (ESCC)." (PMID 39215785, 2025). "In esophageal squamous cell carcinoma (ESCC), SIRT7 deacetylates the promoter of E74 like ETS transcription factor 3 (ELF3), rendering it no longer able to suppress miR-144-3p, a posttranscriptional suppressor of zinc finger E-box binding homeobox 1/2 (ZEB1/2) EMT markers." (PMID 37676263, 2024).
glioblastoma (3 papers, 2022 to 2025). The most malignant astrocytic tumor (WHO grade IV). "Functionally, both gain- and loss-of-function assays confirmed that SIRT7 is essential for maintaining glioblastoma cell growth and survival." (PMID 41114868, 2025). "Once we verified that SIRT7 is truly a downstream target of miR-148a-3p, our next move was to explore whether miR-148a-3p exerts functional effects on glioblastoma cell behavior through this regulatory association." (PMID 41114868, 2025). "The findings imply that the inhibition of SIRT7 augmented the cytotoxic potential of temozolomide (TMZ) in glioblastoma cells." (PMID 41114868, 2025). "The findings gathered from this research offered considerable proof in favor of the hypothesis that miR-148a-3p has a regulatory impact on the progression of glioblastoma cells by specifically zeroing in on SIRT7." (PMID 41114868, 2025). "Notably, SIRT7 knockdown sensitized glioblastoma cells to TMZ-induced apoptosis and growth inhibition, and this effect was confirmed by subcutaneous tumorigenesis in nude mouse." (PMID 41114868, 2025). "Moreover, we demonstrated that the inhibition of SIRT7, achieved either through miRNA overexpression or shRNA - mediated down - regulation, restricted the proliferation of glioblastoma cells." (PMID 41114868, 2025). "Interestingly, SIRT7 knockdown enhanced TMZ-induced cytotoxicity in vitro and potentiated TMZ antitumor effects in glioblastoma xenografts." (PMID 41114868, 2025). "In human U251 glioblastoma (GBM) and HEK-293 cells, KAT2A depletion expectedly decreased the level of Ksuc in specific gene promoter sites; SIRT7 is recruited to DNA DSBs dependent on poly(ADP-ribose) polymerase 1 (PARP1), thereby promoting DSB repair and chromatin condensation." (PMID 38315203, 2024).
head and neck cancer (3 papers, 2019 to 2023). A primary or metastatic malignant neoplasm affecting the head and neck. "For head and neck cancer, however, SIRT7 was upregulated in two unique analyses and downregulated in two unique analyses." (PMID 35136826, 2022).
heart failure (3 papers, 2020 to 2023). Inability of the heart to pump blood at an adequate rate to meet tissue metabolic requirements. "Compared to SIRT1, SIRT3, and SIRT6, studies on SIRT2,541 SIRT4, SIRT5,542 and SIRT7 in heart failure are limited." (PMID 36581622, 2022). "Studies on SIRT2, SIRT4, SIRT5, and SIRT7 might reveal promising research directions for the treatment of heart failure." (PMID 36581622, 2022).
inflammatory bowel disease (3 papers, 2022 to 2025). A spectrum of small and large bowel inflammatory diseases of unknown etiology. "Additionally, elevated SIRT7 levels are implicated in inflammatory bowel disease, while inhibiting SIRT7 ameliorates disease progression by reducing inflammatory factor expression, further validating its pro-inflammatory role." (PMID 40884727, 2025). "Given that SIRT7 is involved in various immune-mediated inflammatory responses (including the NF-kB inflammatory pathway), SIRT7 may, therefore, be closely associated with intestinal immune-mediated inflammatory responses, such as inflammatory bowel disease (IBD)." (PMID 37483618, 2023).
lung adenocarcinoma (3 papers, 2020 to 2024). A carcinoma that arises from the lung and is characterized by the presence of malignant glandular epithelial cells. "Bioinformatics analysis of human lung adenocarcinoma patient samples revealed increased expression of SIRT7 in tumors compared to healthy tissues." (PMID 38870055, 2024). "Bioinformatics analysis of transcriptome data from human lung adenocarcinomas revealed a correlation between SIRT7 expression and increased activity of genes normally repressed by ARF." (PMID 38870055, 2024).
Osteopenia (3 papers, 2018 to 2022). Osteopenia is a term to define bone density that is not normal but also not as low as osteoporosis. "SIRT7 deficiency leads to the development of severe osteopenia due to inadequate osteoblastic differentiation." (PMID 35585284, 2022). "Meanwhile, SIRT7-deficient mice showed several signs of aging, including kyphosis, loss of subcutaneous fat, degenerative cardiac hypertrophy, severe osteopenia, and poor resistance to stress." (PMID 35585284, 2022). "Knockout studies of another deacetylase, Sirt7, found that mice developed osteopenia as Sirt7 interacted with Osterix, deacetylating K368, increasing its transactivation and function." (PMID 32794139, 2020). "Next, we performed static and dynamic bone histomorphometric analysis of the lumbar spine (L4) to investigate the mechanism of osteopenia in Sirt7 KO mice." (PMID 30026585, 2018). "This study provided evidence that Sirt7 KO mice developed severe osteopenia due to decreased bone formation along with an increase of osteoclasts." (PMID 30026585, 2018). "Germline Sirt7 knockout mice develop severe osteopenia characterized by decreased bone formation and an increase of osteoclasts." (PMID 30026585, 2018). "Taken together, these findings indicated the development of severe osteopenia in Sirt7 KO mice." (PMID 30026585, 2018).
progeria (3 papers, 2016 to 2023). "EC-specific restoration of SIRT7 by recombinant adeno-associated virus serotype 1 ameliorated aging features and extended life span in progeria mice." (PMID 34220553, 2021). "They observed a SIRT7-related defective microvasculature and inflammatory response and alleviated the disease phenotype as well as extended the lifespan in progeria mice by delivering SIRT7 via AAV1." (PMID 37008065, 2023). "Recently, it was found that SIRT7 expression was reduced in the vascular endothelium of a mouse model of progeria–a premature aging syndrome." (PMID 34220553, 2021). "In addition, 14 month‐old SirT7−/− mice had reduced IGF‐1 levels in plasma compared with WT littermates, as has been observed in different human and mouse progeroid syndromes." (PMID 27225932, 2016).
prostate adenocarcinoma (3 papers, 2017 to 2024). "panel A) while the expression of SIRT7 was detected in tumor cells as illustrated by a nuclear staining of tumor cells in the prostate adenocarcinoma area." (PMID 29100388, 2017).
psoriasis (3 papers, 2021 to 2024). An autoimmune condition characterized by red, well-delineated plaques with silvery scales that are usually on the extensor surfaces and scalp. "There is a significant reduction in the expression of SIRT1, SIRT2, SIRT3, SIRT4 and SIRT5 and an increase in the expression of SIRT6 and SIRT7 in psoriasis." (PMID 37445960, 2023). "Based on their activity, SIRT1–SIRT5 agonists and SIRT6 and SIRT7 inhibitors may represent new therapeutic options for the treatment of psoriasis, but more studies are needed to confirm this eventuality." (PMID 37445960, 2023). "In light of the analysis of the mode of action of SIRTs in psoriasis, SIRT1–SIRT5 agonists and SIRT6 and SIRT7 inhibitors may represent new therapeutic options for the treatment of psoriasis." (PMID 37445960, 2023). "Psoriasis shows reduced SIRT1-5 expression and increased SIRT6 and SIRT7 expression." (PMID 38892253, 2024). "The dysregulation of this auto-regulatory loop could be also due to the abnormal expression of SIRTs in psoriasis, with the downregulation of SIRT1, SIRT2, SIRT3, SIRT4, and SIRT5 and upregulation of SIRT6 and SIRT7 in skin lesions skin, as previously reported." (PMID 34202251, 2021).
pulmonary hypertension (3 papers, 2024 to 2025). Increased pressure within the pulmonary circulation due to lung or heart disorder. "Moreover, in pulmonary arterial endothelium cells, the overexpression of SIRT7 reversed EC dysfunction occurring under pulmonary hypertension by deacetylating and stabilizing KLF4." (PMID 38791128, 2024). "In parallel, emerging evidence indicates that SIRT7 overexpression attenuates endothelial cell inflammatory responses by regulating KLF4 deacetylation and ameliorates pulmonary hypertension." (PMID 40884727, 2025). "During pulmonary arterial hypertension (PAH) pathogenesis, SIRT7 upregulates AKT in a JNK-dependent manner that, in turn, activates lipogenic enzymes ATP-citrate lyase and acetyl-CoA carboxylase, promotes lipid deposition, and remodels the pulmonary vasculature in favor of PAH." (PMID 37676263, 2024).